CCL21 (C-C motif chemokine ligand 21)
Diseases named in the same sentence as CCL21 in open-access papers (continued):
Sharing a sentence is not in itself a finding about the gene and the disease.
latent infection (2 papers, 2018 to 2021). "CCL19, CCL21, IL-7, and IL-15 are known to promote latent infection in resting CD4+ T-cells." (PMID 29997630, 2018). "As such, chemotactic stimulation, such as stimulating resting CD4 T cells with the chemokines CCL19/CCL21, has been shown to activate the cofilin pathway and thereby promote HIV latent infection of resting T cells." (PMID 34765923, 2021). "In contrast to CD2 signaling, prestimulation of resting CD4 T cells with anti-CXCR4 antibody, with the chemokines CCL19/CCL21, or with IP-10 (CXCL10) has been shown to promote HIV-1 latent infection of resting CD4 T cells." (PMID 34765923, 2021).
Lewis lung carcinoma (2 papers, 2010 to 2012). "Similarly, another DNA-based vaccine encoding SVN and chemokine CCL21 was shown to inhibit angiogenesis and induced potent CD8+ T cell and IFN-γ responses against Lewis lung carcinoma with significant prophylactic and therapeutic efficacy." (PMID 23144888, 2012). "With these considerations in mind, we found that pre-treatment of LEC with heparinase (to destroy cell-surface HS) inhibited murine Lewis lung carcinoma (LLC) invasion into the LEC-embedded collagen, a process that was also CCL21 dependent." (PMID 21172016, 2010).
Lipedema (2 papers, 2020 to 2022). Disorder of adipose tissue characterized by symmetric and bilateral enlargement of the lower extremities due to abnormal deposition of subcutaneous fat often in obese women. "The expression levels of other lymphatic-related genes, such as podoplanin (PDPN), PROX-1, lymphatic-vessel endothelial hyaluronan receptor 1 (LYVE1), and C-C motif chemokine ligand 21 (CCL21), were similar in lipedema fat tissue compared to healthy controls." (PMID 36551837, 2022). "No significant changes were observed for most of the common lymphatic markers, namely PDPN, PROX-1, LYVE-1, CCL21 but a 1.9-fold (P = 0.02) increase was observed in the expression of VEGFR-3 in lipedema in comparison to the control." (PMID 32616854, 2020).
lymphopenia (2 papers, 2012 to 2024). Reduction in the number of lymphocytes. "A trend towards a decrease in the irradiated DLNs was also observed in the concentration of CCL21 (right), suggesting that sustained lymphopenia associated with DLN IR might indeed be due to a perturbance in the CCR7-CCL19/CCL21 axis." (PMID 38951172, 2024). "In line with the data on the lymph node composition of CCL19- and CCL21-deficient plt mice, we hypothesized that this decrease in the cell surface expression of the receptor was a consequence, rather than the cause of the observed lymphopenia in the irradiated lymph nodes." (PMID 38951172, 2024).
mycosis fungoides (2 papers, 2021 to 2022). Classical mycosis fungoides is the most common type of mycosis fungoides (MF), a form of cutaneous T-cell lymphoma, and is characterized by slow progression from patches to more infiltrated plaques and eventually to tumors. "Elevated CCR7 presence was also found on the membrane of MyLa cells derived from a patient with mycosis fungoides that showed migration to CCL21 mediated via the mTOR pathway." (PMID 35203305, 2022).
neuroblastoma (2 papers, 2022 to 2025). Neuroblastoma (NB) is the most common solid, extracranial childhood tumor. "High expression levels of CCL2, CCL4, CCL21, CD200, CXCR3, and IGSF6 were significantly associated with improved survival in neuroblastoma patients (all p < 0.001)." (PMID 40718780, 2025). "In our study, we identified four chemokines, CCL2, CCL4, CCL21, and CXCR3, in neuroblastoma samples, which may originate from different cellular subsets." (PMID 40718780, 2025). "Our study demonstrates that tertiary lymphoid structure (TLS)-related genes play a crucial role in neuroblastoma (NB) prognosis, with a 6-gene TLS signature (CCL2, CCL4, CCL21, CD200, CXCR3, and IGSF6) serving as a promising prognostic biomarker for NB." (PMID 40718780, 2025).
Obesity (2 papers, 2013 to 2020). Accumulation of substantial excess body fat. "Thus, our nanoString screen suggests that in renal tumors from subjects with obesity, increases in CD36 and IDO1, with concomitant decreases in T cell-related CD7 and CCL21, are consistent with a host environment that favors tumor progression." (PMID 32469992, 2020). "Of those changes identified in the tumor microenvironments of ccRCC subjects with obesity versus non-obese counterparts, those with the largest fold changes were CD36 (+2.514, P = 0.045), IDO1 (+2.46, P = 0.012), CFB (+2.0, P = 0.041), CD7 (-4.66, P = 0.046), and CCL21 (-5.28, P = 0.0097)." (PMID 32469992, 2020).
oral cancer (2 papers, 2020 to 2022). "Additionally, previous research has considered CCL21 in oral cancer as a candidate marker for unfavorable outcome." (PMID 32961854, 2020).
ovarian tumors (2 papers, 2008 to 2018).
peripheral nerve injury (2 papers, 2019 to 2022). Injury to a peripheral nerve. "Several studies have analyzed the role of CCL21 in NeP in a peripheral nerve injury model, but little is known in SCI, including the effects on M1- and M2-type microglia/macrophage chemotaxis at the injured site and in remote regions." (PMID 31824269, 2019). "In a peripheral nerve injury model, CCL21 is only expressed in damaged neurons and induces upregulation of the P2X4 receptor in microglia and macrophages." (PMID 31824269, 2019). "In a peripheral nerve injury model, there was no increase in pain for 10 days after withdrawal of a CCL21-blocking antibody." (PMID 31824269, 2019).
pulmonary arterial hypertension (2 papers, 2020 to 2022). Pulmonary arterial hypertension (PAH) is a group of diseases characterized by mean pulmonary artery pressure >20 mmHg and elevated pulmonary arterial resistance leading to right heart failure. "Of these chemokines and chemokine receptors, Ccl2, Ccl7, Ccl20, Ccl21, Cxcl13, Cxcl4, Ccr6 and Ccr7 have already been demonstrated to be associated with pulmonary hypertension." (PMID 32176619, 2020). "We recently identified altered levels of chemokine CCL21 in SSc associated pulmonary arterial hypertension (PAH)." (PMID 36211384, 2022).
pulmonary disease (2 papers, 2022 to 2023). "It was found that smoking may correlate with elevated CCR7 mRNA expression level, that CCR7 plays a major role in modulating inflammatory responses in airways in pulmonary diseases, and that cigarette smoking upregulates CCR7, CCL19, and CCL21 mRNA expression levels in lymph nodes of wild-type mice." (PMID 35160116, 2022).
Sepsis (2 papers, 2021 to 2024). Sepsis is defined as life-threatening organ dysfunction caused by a dysregulated host response to infection. "Meanwhile, VEGF-C156S posttreatment reversed sepsis-inhibited CC chemokine ligand 21 (CCL21), which colocalizes with pulmonary lymphatic vessels." (PMID 37971881, 2024). "We further showed that CCL21 was colocalized with Prox1 in pulmonary lymphatic vessels and was also reduced notably in sepsis-induced ARDS." (PMID 37971881, 2024). "Prior blocking of VEGFR-3/CCL21 also worsens sepsis-induced lymphatic dysfunction and inflammation." (PMID 37971881, 2024). "We detected that several classical lymphatic markers such as CCL21 were markedly decreased in sepsis, while VEGF-C156S posttreatment could reverse those changes." (PMID 37971881, 2024). "Moreover, prior blocking of CCL21 worsened sepsis-induced accumulation of inflammatory cells, indicating that CCL21 played an important role in the migration of inflammatory cells." (PMID 37971881, 2024). "In addition, MAZ51 or anti-CCL21 antibody also abolished the survival benefit of VEGF-C156S for sepsis mice." (PMID 37971881, 2024). "In addition, prior blocking of VEGFR-3 or CCL21 augmented sepsis-induced mortality." (PMID 37971881, 2024). "We observed that CCL21 was colocalized with Prox1-tdTomato in pulmonary lymphatic vessels; moreover, the area coverage and the relative intensity of CCL21+ cells were significantly decreased in sepsis, while VEGF-C156S posttreatment could increase LPS-inhibited CCL21 expressions simultaneously." (PMID 37971881, 2024).
squamous cell carcinoma (2 papers, 2014 to 2015). A carcinoma arising from squamous epithelial cells. "This idea is further supported by the observation of a significantly higher rate of tumor growth in wild-type BALB/c mice compared to plt mice, which lack CCL19 and CCL21, implanted with a syngeneic squamous cell carcinoma cell line." (PMID 24700353, 2014).
T cell lymphoma (2 papers, 2011 to 2016). "CCL19 and CCL21 have been reported to have the same efficacy and potency in G protein activation (in H9 T cell lymphoma cells) and Ca2+ flux (in L1.2 cells, a murine pre-B cell line)." (PMID 28018341, 2016). "Therefore, the ideal CCL21 concentration for CCR7 expression in T cell lymphoma is 50-100 nmol/L." (PMID 21548969, 2011).
tauopathies (2 papers, 2022 to 2025). "The results for CTE compared to the other tauopathies with just males was consistent with CCL21 as the most predictive CTE protein." (PMID 36403052, 2022).
visceral leishmaniasis (2 papers, 2012 to 2013). A severe form of leishmaniasis characterized by irregular bouts of fever, substantial weight loss, swelling of the spleen and liver, and anemia (which may be serious). "Furthermore, in a visceral leishmaniasis model, CCL21 expression correlates with parasite burden in the dermis of infected dogs." (PMID 24205367, 2013).
vitiligo (2 papers, 2023 to 2024). Generalized well circumscribed patches of leukoderma that are generally distributed over symmetric body locations and is due to autoimmune destruction of melanocytes. "CCR7 and its ligand CCL21 are also involved in Treg migration and CCL21 is significantly decreased in vitiligo skin." (PMID 39274437, 2024). "Several studies demonstrate reduced levels of CCL5/CCR4, CCL22, CCL21, and CCR6 in vitiligo skin, which could explain the failure of circulating Tregs to localize to the skin, thus suggesting that the modulating expression of these chemokines may be potential therapeutic targets in vitiligo." (PMID 36675037, 2023).
acute kidney injury (1 paper, 2010). Sudden and sustained deterioration of the kidney function characterized by decreased glomerular filtration rate, increased serum creatinine or oliguria. "Increased tubular nuclear RelB and tubular CCL21 expression in acute kidney injury were decreased by neutralization (2±0.9 vs 1.3±0.6-fold over healthy control) or deficiency of TWEAK (2±0.9 vs 0.8±0.6-fold over healthy control)." (PMID 20126461, 2010).
acute respiratory distress syndrome (1 paper, 2017). Progressive and life-threatening pulmonary distress in the absence of an underlying pulmonary condition, usually following major trauma or surgery. "As it has been shown that CXCL13 and CCL21 have synergistic effects in lymphoid tissue production in RA synovitis and more recently that CCL7 has been shown to synergise with CXCL8 in acute respiratory distress syndrome to promote neutrophil migration." (PMID 28648867, 2017).
adenoma (1 paper, 2011). A neoplasm arising from the epithelium. "CCL19, CCL21, CCL23, CCL5, were found to have reduced expression in the adenoma and adenocarcinoma compared to normal mucosa." (PMID 21249124, 2011).
allergic conjunctivitis (1 paper, 2014). "Antagonists of CCL21 seem to prevent the development of chronic graft versus host disease or reduced allergic conjunctivitis by blocking CCR7 in mice." (PMID 25254213, 2014).
allergic contact dermatitis (1 paper, 2025). An inflammatory skin condition caused by an immune response to direct contact between the skin and an allergen. "In human skin, both CCL21 mRNA and protein expression were found to be upregulated in LECs in allergic contact dermatitis patients during an allergic inflammatory response." (PMID 40281034, 2025).
allergic rhinitis (1 paper, 2012). Inflammation of the nasal mucous membranes caused by an IgE-mediated response to external allergens. "Nasal administration of plasmids encoding CCL19/CCL21-Ser-DNA suppressed allergic responses in the murine allergic rhinitis model." (PMID 23118775, 2012). "We formerly showed the regulatory role of CCL19 and CCL21 in allergic rhinitis." (PMID 23118775, 2012).
amyotrophic lateral sclerosis (1 paper, 2021). Amyotrophic lateral sclerosis (ALS) is a neurodegenerative disease characterized by progressive muscular paralysis reflecting degeneration of motor neurons in the primary motor cortex, corticospinal tracts, brainstem and spinal cord. "As a well-studied neuronal chemokine, the pathological expression of CCL21 has been detected in cerebral ischemia, axonal injury, amyotrophic lateral sclerosis, and spinal cord injury." (PMID 34595235, 2021).
ankylosing spondylitis (1 paper, 2014). An autoimmune chronic inflammatory disorder characterized by inflammation in the vertebral joints of the spine and sacroiliac joints. "However, the role of CCL19/CCL21 in ankylosing spondylitis is rarely reported and demands a more comprehensive understanding." (PMID 25260647, 2014).
aortic valve calcification (1 paper, 2014). "There was a significant association between CCL21 and backscatter as a marker of aortic valve calcification, and in particular with decreased aortic valve area." (PMID 25398010, 2014).
Atherosclerotic lesion (1 paper, 2022). A lesion associated with atherosclerosis, a multifactorial and multipart progressive disease manifested by the focal development within the arterial wall of lesions, that ranges from the development of a fatty streak, plaque progression, and plaque disruption. "Further, while the levels of CCL19 and CCL21 in the plasma in atherosclerotic lesions have been noticed, both these molecules are reported to be upregulated in carotid AS." (PMID 36187128, 2022).
atrial fibrillation (1 paper, 2014). A disorder characterized by an electrocardiographic finding of a supraventricular arrhythmia characterized by the replacement of consistent P waves by rapid oscillations or fibrillatory waves that vary in size, shape and timing and are accompanied by an irregular ventricular response. "Patients with high CCL21 levels were also more likely to be males, to have accompanying CAD and atrial fibrillation, to use ß-blockers and warfarin and to have a lower body mass index (BMI)." (PMID 25398010, 2014).
atrophic gastritis (1 paper, 2020). "In an atrophic gastritis environment, the expression of CXCL14, CCL4, CCL26, CCL21, CCL2, CCL19, and CCL13 was correlated with the infiltration of central memory CD4 T cell." (PMID 33426088, 2020).
autoimmune uveitis (1 paper, 2022). An autoimmune form of uveitis (disease). "Reduced intensity of autoimmune uveitis with reduced infiltration of T cells, as well as reduced effects of CCL2 and CCL21, chemo-attractive factors for inflammatory cells, were established in their studies." (PMID 35986305, 2022).
B-cell lymphoma (1 paper, 2025). "Top proteins specifically associated with germinal center-derived B-cell lymphoma risk included LSAMP, FDCSP, SERPINA9, CCL21 and CD40LG." (PMID 40894013, 2025).
Burkitt lymphoma (1 paper, 2024). A rare form of malignant mature B-cell non-Hodgkin lymphoma. "Consistent with this, we found that the KO of ACKR4 in Raji Burkitt lymphoma cells led to a dramatic increase in CCL21-guided cell migration." (PMID 39298333, 2024). "(F) The knockout of ACKR4 in Burkitt lymphoma Raji cells increases their CCL21-guided migration." (PMID 39298333, 2024).
chronic heart failure (1 paper, 2024). "CCL21 is also associated with detrimental effects including associations with all-cause mortality, myocardial inflammation and fibrosis, and chronic heart failure." (PMID 38999835, 2024).
Cirrhosis (1 paper, 2022). A chronic disorder of the liver in which liver tissue becomes scarred and is partially replaced by regenerative nodules and fibrotic tissue resulting in loss of liver function. "Upon detailed assessment, cytokine levels and cirrhosis etiology revealed that HBV-cirrhosis—regardless of antiviral therapy—had a 3-fold increase in IFN-γ, TRAIL and CXCL1 (GRO-α) levels and up to 3-fold decrease in MMP-2, CXCL12, IL2RA, IL-6Rα, CCL2 (MCP1) and CCL21 (6kine) levels." (PMID 36230823, 2022).
clear cell renal cell carcinoma (1 paper, 2017). "Further stratified analysis showed that low CCL21 expression was significantly associated with shorter overall survival in clear cell renal cell carcinoma patients (P = 0.017) and patients treated with sorafenib (P = 0.009)." (PMID 27783999, 2017). "Low CCL21 expression still indicated shorter OS in patients with clear cell renal cell carcinoma (P = 0.017) and patients treated with sorafenib (P = 0.009)." (PMID 27783999, 2017).
CNS lymphoma (1 paper, 2019). "Further, we provide evidence that APRIL and BAFF induce chemotaxis of systemic and CNS lymphoma cell lines, confirming previously published results showing that BAFF increases the chemotactic response of human B cells to CXCL12, CXCL13, and CCL21 in vitro." (PMID 31615554, 2019).
cognitive decline (1 paper, 2020). "In different degrees of SCI mouse models, the upregulation of CCL21 and the activation of microglia can be seen, as well as neuron loss, hippocampal neurogenesis, and cognitive decline." (PMID 33376730, 2020).
colorectal adenocarcinoma (1 paper, 2021). The most common type of colorectal carcinoma. "Various studies have shown that elevated levels of CCL21/CCR7 lead to migration and proliferation of cancerous cells, although decreased expression of CCL21 was reported in human colorectal adenocarcinoma." (PMID 33829064, 2021).
colorectal tumor (1 paper, 2022). "Murine colorectal tumor cell lines (CT26 and MC38) stably overexpressing mouse C-C motif chemokine ligand 3 (CCL3), CCL19, CCL21, and X-C motif chemokine ligand 1 (XCL1) were established by lentiviral transduction." (PMID 36654820, 2022).
cyst (1 paper, 2007). A sac-like closed membranous structure that may be empty or contain fluid or amorphous material. "In some ectopic peritoneal lesions, large irregular cyst-like structures were present and strong staining for both CCL16 and CCL21 was apparent in glandular epithelial cells and in secretions within the cyst." (PMID 17506907, 2007).
dacryoadenitis (1 paper, 2016). Inflammation and enlargement of the lacrimal gland. "In this study, we discuss the pathological feature of ectopic lymphoid neogenesis in idiopathic dacryoadenitis, as well as the expression of follicular dendritic cells (FDCs), CXCL 13 and CCL21." (PMID 27230507, 2016). "Some research has reported that the expression of CCL21 increased in tissue containing ectopic GC reactions, but we could not confirm this in idiopathic dacryoadenitis; the function of CCL21 in this disease needs further discussion." (PMID 27230507, 2016).
depression (1 paper, 2021). "Although we did not specifically examine this, it is tempting to speculate that the up-regulation of CCL21 reported here might have a bearing on the higher than average incidence of depression, common in BPS." (PMID 34876093, 2021).
emphysema (1 paper, 2025). "Interestingly, Thy1 and Ccl21 were increased in GOLD 1-2 patients with emphysema and prominent TLOs compared with GOLD 1-2 patients without emphysema." (PMID 39437762, 2025).
encephalitis (1 paper, 2016). An acute inflammatory process affecting the brain parenchyma. "IL-4 CCL11, CCL17, CCL21), Th17 (IL-17A, GM-CSF), B cell molecules (BAFF, APRIL) and other cytokine/chemokines including IL-21, IL-1b, IL-12p40, CCL2 and IL-12p70 were detected in less than 50% of patients with encephalitis." (PMID 27575749, 2016).